BDNF (brain derived neurotrophic factor)
Diseases named in the same sentence as BDNF in open-access papers (continued):
Sharing a sentence is not in itself a finding about the gene and the disease.
tumor (continued). "Recently, extensive studies have shown that BDNF and TRKB are upregulated in many types of cancer, including EC, endowing tumor cells with an aggressive phenotype, such as EMT and chemotherapy resistance." (PMID 36721236, 2023). "GBM cells experience crosstalk with the nervous system through paracrine interactions involving brain-derived neurotrophic factor (BDNF) and NLGN3 proteins, additionally contributing to tumour growth and survival." (PMID 37686652, 2023). "During the regression period, brain-derived neurotrophic factor (BDNF) activates TGF-β to induce a transformation between the growth and regression phases and promotes tumor regression by binding to TrkB." (PMID 38254620, 2023). "We first investigated the upregulated four genes (BDNF, PTGS2, CTNNB1, and GSK3B) in the tumor sample expression profile in CC patient tissue using RNAseq data." (PMID 35054980, 2022). "ADRB2, ANGPTL4, BDNF, CBLC, CX3CR1, and IL3RA were found markedly different expression between the tumor and normal group." (PMID 35833114, 2022). "Four genes (BDNF, PTGS2, GSK3B, and CTNNB1) were significantly upregulated and one gene (HPGD) was significantly downregulated in primary tumor tissues compared with adjacent normal tissues throughout all the five in silico datasets." (PMID 35054980, 2022). "In patients with CRC, the high serum levels of BDNF and NT4/5 cannot be considered markers of disease progression or tumor stage, but rather can be used as indicators of good prognosis." (PMID 36263167, 2022). "In brief, NGF, the Brain-Derived Neurotrophic Factor (BDNF), Neutrophin 3 (NTF3) and Neutrophin 4 (NTF4) are the major neurotransmitters secreted by neural and tumour cells in PDAC." (PMID 36497277, 2022). "We found that four muscle failure-related genes (BDNF, FNDC5, IL15, MSTN) were significantly increased in tumor cells." (PMID 36733390, 2022). "Then, we examined the mRNA expression levels of BDNF, FNDC5, IL15, and MSTN, in tumor tissues and paracancerous tissues." (PMID 36733390, 2022). "Other neurotrophic factors such as brain-derived neurotrophic factor (BDNF) and glial cell-derived neurotrophic factor (GDNF), have been shown to induce tumor migration via upregulation of VEGF and activation of p38 and PI3K/Akt signaling pathway." (PMID 35223829, 2022). "We examined the mRNA expression of four myokine/exerkine genes, BDNF, FNDC5, IL15, and MSTN, in tumor and paraneoplastic tissues." (PMID 36733390, 2022). "These B cells predominately produced IgA that specifically recognized these targets expressed in HGSOC tumour cells, as well as recombinant TSPAN7 and BDNF." (PMID 33536615, 2021). "Through a series of experiments in vitro and in vivo, they also showed that BDNF activates TrkB, which leads to upregulation of Akt signaling, induction of EMT, tumor progression, and increased migration and invasion in head and neck SCC." (PMID 34885121, 2021). "Moreover, the down-regulation of miR-107 may cause cell cycle and proliferation due to the up-regulation of CDK6 (also targeted by miR-103) and CDK8 and metastasis and tumor growth because of the up-regulation of BDNF as well as indirect regulating of the P13K/AKT signaling pathway." (PMID 34635059, 2021). "Our analysis revealed that the serum levels of BDNF were significantly higher in patients with CRC compared with those of HC, which were consistent with the upregulation of its expression in CRC tumor tissues." (PMID 33628340, 2021). "Next, we examined the mRNA expression of BDNF and CYSLTR1 in tumor and its matched normal tissue samples from CRC patients and the qRT-PCR analysis significantly showed upregulation in tumor samples compared to its normal tissue samples for both genes." (PMID 34771682, 2021). "We then analysed relationships between BDNF concentrations and different oncological parameters, such as TNM staging, lymph nodes, neural and vascular invasions, histologic grade, and tumour size." (PMID 34395067, 2021).
tumor (continued). "Compared with A375 cells, A375 xenograft tumor displayed an upregulation for glial and neuronal genes (GFAP, BDNF, MAP2, MTURN, ROBO2, SYT1 and TUBB3) and neural stemness genes (ASCL1, MSI1, PAX6, PDGFRA, SOX9, VIM, ZIC1/2)." (PMID 33468253, 2021). "The ROC analysis result was also convincing in TCGA-COAD dataset and the best fit multivariate Cox models using CD66b, BDNF, CYSLTR1 expression in tumor tissues and the significant clinical factors (age, LNM and TNM) was achieving high AUC values (AUC = 0.73)." (PMID 34771682, 2021). "In PDAC, tumor cells secrete NGF and BDNF, which act on Tropomyosin-related kinase (Trk) receptors to stimulate nerve growth." (PMID 33322770, 2020). "The present study shows that over-expressed MEGF11 upregulates the gene expression of BDNF/TrkB in TNBC cells, which suggests that MEGF11 plays a role in tumour cell-endothelial cell interactions." (PMID 32415115, 2020). "In this case, tumor cells secrete NGF and BDNF (brain-derived neurotrophic factor) stimulating nerve growth via their Trk receptors (Tropomyosin-related kinase receptors)." (PMID 32555170, 2020). "Activated fibroblasts, which also produce increased levels of BDNF, were capable of induction of EMT in tumor cells." (PMID 30641914, 2019). "Brain-derived neurotrophic factor was detected at mRNA level in normal mucosa and in HNSCC tumor tissue by RT-PCR and by in situ hybridization." (PMID 30641914, 2019). "In OSCC tumor lesion, TRKB and BDNF were highly expressed in infiltrated immune cells and tumor-associated vessels as well as in tumor cells." (PMID 29861866, 2018). "We also noted that tumor growth led to downregulation of NPAS4, BDNF, and several other neurotrophic factors." (PMID 29556248, 2018). "First, the expression levels of TRKB and/or its specific ligand, BDNF, were significantly higher in MD/PD-OSCC tumor cells than in WD-OSCC tumor cells." (PMID 29861866, 2018). "The observed concomitant downregulation of AKT1, ERK1/2, NPAS4, BDNF, and other NPAS4 targets strongly suggests the importance of these pathways in tumor brain, as it manifests in the hippocampus." (PMID 29556248, 2018). "Next, to examine the tumor differentiation and the TRKB/BDNF expressions in this transplantation model, H&E staining and immunohistochemistry were performed using the tumor tissues 21 days after transplantation." (PMID 29861866, 2018). "In summary, we report here a new correlation between TRKB/BDNF overexpression and OSCC tumor differentiation using human tissue specimens, and propose TRKB as an attractive therapeutic target for OSCC." (PMID 29861866, 2018). "TrkB is activated in NB via the endogenous expression of brain-derived neurotrophic factor (BDNF), and increased TrkB expression is an indicator of poor disease prognosis, since TrkB overexpression can lead to tumor cell growth and metastasis." (PMID 29898774, 2018). "We describe a new correlation between TRKB/BDNF overexpression and OSCC tumor differentiation, and propose that TRKB is a potential therapeutic target for OSCC, especially for poorly differentiated OSCC." (PMID 29861866, 2018). "Collectively our results suggest that BDNF signaling to BBM cells supports colonization and tumor growth in the brain microenvironment." (PMID 28446206, 2017). "In the current study, we found that BDNF stimulated the secretion of estradiol and progesterone, and increased the proliferation of KGN cells (human granulosa-like tumor cell line)." (PMID 28282971, 2017). "With this in mind, using western immunoblotting, we analyzed the levels of BDNF in the PFC tissues of intact controls, and TNBC and PR+BC tumor-bearing treated and untreated mice." (PMID 29179434, 2017). "The suppression of BDNF in the CAF compartment led to decreased tumor growth, suggesting that CAF-derived BDNF is a critical mediator of in vivo tumor growth." (PMID 28966935, 2017).
tumor (continued). "Among these target genes, the expression of BDNF, MEIS1, FOXC1, NUAK1, RAB22A, and XRN1 is inversely correlated with that of miR-204 in those tumor specimens examined, strongly suggesting that miR-204 is one of the key suppressors of the target genes." (PMID 27438705, 2016). "Since BDNF overexpression was common in more aggressive tumours, the stable cells of LK2 or A549 with low expression of BDNF were used to determine its contribution to cell invasion." (PMID 26926340, 2016). "Tropomyosin-related receptor kinase B (TrkB) signaling, stimulated by brain-derived neurotrophic factor (BDNF) ligand, promotes tumor progression, and is related to the poor prognosis of various malignancies." (PMID 24801982, 2014). "Afterwards the BDNF and LY96 mRNA levels were determined in the same tumor tissue samples and compared to the SFRP1 expression level in the particular tumor sample." (PMID 25036590, 2014). "Therefore, BDNF may be a novel target for tumor detection and chemotherapy." (PMID 23892595, 2013). "Another five genes that were up-regulated with tumor progression showed further increased expressions after chemotherapy (CRISP3, KCNMA1, BDNF, SLC22A4, SYN2)." (PMID 23451142, 2013). "We demonstrated that miR-204 exerts its function by targeting genes involved in tumorigenesis including brain-derived neurotrophic factor (BDNF), a neurotrophin family member which is known to promote tumor angiogenesis and invasiveness." (PMID 23285024, 2012). "These preliminary data are in accordance with our findings with the cell lines, pointing-to the activation of the BDNF/TrkB machinery in CRC tissues and its likely critical role in tumor growth." (PMID 21966426, 2011). "Similar to the process by which tumor cells induce angiogenesis by secreting vascular endothelial growth factor (VEGF) family factors, they can also secrete neurotrophic factors, including BDNF, NGF, NTF3, and NTF4." (PMID 41556039, 2026). "Tumor cells overproduce neurotrophic factors (such as NGF and BDNF) and axon guidance molecules (like Netrin‐1), which attract nerve fibers into the tumor and may promote new nerve formation." (PMID 41583906, 2026). "Similarly, ovarian cancer cells upregulate BDNF expression via the ADRB3/cAMP/Epac/JNK axis in response to catecholamines, inducing axonogenesis and increasing the density of nerves in the tumor mass." (PMID 41556039, 2026). "Molecular profiling of tumor tissue or exosomes for neurotrophic factors (NGF, BDNF, GDNF), chemokines (CXCL12, CCL2), or neuronal transcription factors (POU4F1) may serve as predictive biomarkers of neural involvement." (PMID 41009819, 2025). "The BDNF antibody likely blocks BDNF signaling (though not directly proven), as the same antibody lacking the Fc domain still retained tumor control ability." (PMID 40356924, 2025). "Brain-derived neurotrophic factor (BDNF), which promotes neuronal maturation and plasticity, was expressed in whole organoids and organoid slices, with reduced levels observed in assembloids with lower expression in tumor-like cells and tumor spheres." (PMID 40917877, 2025). "BDNF is a well-known factor that contributes to the development of SCZ and tumor." (PMID 38592583, 2024). "We thus determined the expression of BDNF and TrkB to see whether these signals contribute to TNFR2-induced tumor development." (PMID 38592583, 2024). "Previous studies have indicated the role of miR-1-3p as a tumor suppressor in different cancers through different mechanisms, such as upregulating SFRP1, repressing E2F5 and PFTAIRE protein kinase 1, and modulating BDNF and TrkB." (PMID 38793064, 2024). "Previous research has shown that BDNF primarily regulates GC proliferation through the PI3K/AKT, NF-kB, and CREB tumour pathways; however, the role of other molecular mechanisms in mediating BDNF-induced GC proliferation remains unclear." (PMID 38397033, 2024).
tumor (continued). "The connection between neurons and OPCs involves paracrine mechanisms, such as the numerous roles of BDNF in neural development and plasticity, IGF signaling in gliomagenesis, and in addition to promoting tumor proliferation mentioned earlier, also facilitating myelin development." (PMID 39469896, 2024). "The infiltrative nature of GBM was highlighted by the lack of a relationship between the tumor volume and the BDNF concentration." (PMID 38050515, 2023). "In the second phase our studies showed no significant increase in serum BDNF concentration in these NB patients, with adverse pathologic features, large tumor maximum diameter, and MYCN amplification." (PMID 37460933, 2023). "The mRNA expression of BDNF, IL15, and MSTN were significantly higher in tumor tissues than in paraneoplastic tissues, while the expression of FNDC5 was significantly reduced in tumor tissues." (PMID 36733390, 2022). "We found, after correcting for tumor volume and location, correlations between the expression level of CD3 or IDH-1 and psychomotor speed; IDH-1, BDNF, ATRX, CK2Beta, GAT-3, NLGN3, SRF, or EAAT1 and memory performance, and P-STAT5b, NLGN3, CK2Beta, or IDH-1 and executive functioning." (PMID 35148403, 2022). "BDNF is a member of neurotrophin family of tyrosine kinase receptors which is involved in regulation of PI3K/AKT, RAS/ERK, PLC/PKC, and JAK/STAT signaling pathways during tumor progression." (PMID 35659780, 2022). "The expression levels of BDNF, IL15, and MSTN were significantly higher in tumor tissues than in paraneoplastic tissues, while the expression level of FNDC5 was significantly reduced in tumor tissues." (PMID 36733390, 2022). "Moreover, we ascertained that the different expression of ADRB2, ANGPTL4, BDNF, CBLC, CX3CR1, and IL3RA in tumor and normal group was consistent both in PCR and UALCAN." (PMID 35833114, 2022). "Overall, the in vitro data on the GBM tumor cell line indicate that, in hypoxic conditions, high levels of p75NTR may correlate with high levels of HIF1A and KDM5C, a negative regulator of BDNF." (PMID 36142158, 2022). "Whether in Oncomine or in UALCAN, ADRB2, ARRB1, BDNF, etc., had a lower expression in tumor group than normal tissues, whereas CBLC, GPI, and PAK1 had a higher expression in tumor group than normal tissues." (PMID 35833114, 2022). "Since GBM contains several tumor microenvironments (TMEs) with irregular distributions of signaling networks, we wondered whether the gene expression levels of KDM5C, BDNF, and HIF1A differed in distinct GBM tumor areas." (PMID 36142158, 2022). "Considering the TNM stages, the postoperative BDNF concentration fell in groups with (p = 0.0218) and without (p = 0.034) distant metastases and in patients with tumours below the median size (p = 0.018)." (PMID 34395067, 2021). "BDNF and HLA-A showed significant difference in methylation between various grades of tumours, but were not involved in stemness, according to our analysis." (PMID 34685742, 2021). "In OSC19 cells, stable TrkB inhibition (through retroviral vectors containing a short hairpin RNA (shRNA) targeting TrkB) blocked BDNF-induced EMT and cell migration, further supporting the role of BDNF/TrkB signaling in tumor progression, migration, and invasion in oral SCC." (PMID 34885121, 2021). "We further analyzed the correlations between serum BDNF and clinicopathologic features of CRC and found that BDNF overexpression was closely associated with tumor differentiation, tumor size, and metastasis, but not with gender or age." (PMID 33628340, 2021). "Serum levels of BDNF (p = 0.017) were also significantly correlated with tumor masses, while CEA (p = 0.193) levels were not." (PMID 33628340, 2021). "To verify the results of our data analysis, we extracted total RNA from different tumour cell lines (HCT116, SW480, HT29, LOVO, RKO, DLD-1) and the normal epithelial colon cell line NCM460 and measured the mRNA expression levels of TIMP1, PLCG2, BDNF and IL13." (PMID 35003085, 2021).
tumor (continued). "We next categorized BDNF tumor expression into two groups: low (negative and weak, found in 24 patients) and high (moderate and strong, in 32 patients)." (PMID 34771682, 2021). "Serum levels of BDNF were significantly higher in patients with CRC with metastasis (6.78 ± 3.68 ng/mL) compared to patients without metastasis (10.30 ± 5.76 ng/mL) (p = 0.007), suggesting that BDNF was related to tumor progression and metastasis in CRC." (PMID 33628340, 2021). "When mice bearing the glioma and not housed in enriched environments were infused with BDNF, they reduced tumor size and macrophage infiltration." (PMID 33096634, 2020). "EVs mainly contained miRNA and proteins, which are known to be metastasis-associated factors such as brain-derived neurotrophic factor (BDNF), C-X-C motif chemokine 12 (CXCL12), and osteopontin, and are potent mediators of communication between tumor cells and stroma." (PMID 32634139, 2020). "This may be of particular relevance in the tumour microenvironment, given that NAS is a brain-derived neurotrophic factor (BDNF) mimic, via its activation at the BDNF receptor, TrkB." (PMID 33375613, 2020). "We also suggest that the up-regulation of brain-derived neurotrophic factor (BDNF), which supports innervation in tumor xenografts, could be a promising determinant of tumor cell invasion and metastasis." (PMID 32093026, 2020). "The average follow-up period was 39 months (ranging from 0 to 130 months) and during this time none of the patients died due to their tumour, hampering our analysis of BDNF and TrkB values as a biomarker for disease-specific survival." (PMID 33255325, 2020). "Additionally, Indo5, selectively abrogating HGF-induced c-Met pathway activation and brain-derived neurotrophic factor (BDNF)/nerve growth factor (NDF)-induced Trks signaling activation, significantly inhibits HCC tumor growth in xenograft mice." (PMID 32117981, 2020). "The results obtained through immunohistochemical analysis of human OSCC tumor specimens showed that the expression levels of TRKB and/or BDNF, were significantly higher in moderately and poorly differentiated OSCC (MD/PD-OSCC) tumor cells than in well differentiated cells (WD-OSCC)." (PMID 29861866, 2018). "TNBC and PR+BC tumor growth also led to a significant decrease in the levels of neuronal transcription factor NPAS4, a regulator that governs the expression of brain-derived neurotrophic factor (BDNF), and several other key brain neurotrophic factors and pro-survival molecules." (PMID 29556248, 2018). "Also, the pathological changes of the tumor, hippocampus, and the expressions of GR, NR2A, NR2B, CAMKII, CREB, and BDNF were detected." (PMID 30581482, 2018). "Consistent with the behavioral data, there was an absence of a tumor effect on BDNF gene expression and DCX + cells (approximate measure of neurogenesis)." (PMID 28811490, 2017). "Although controversy still exits as to the exact role of BDNF in tumor suppression and promotion, information concerning BDNF-related cancer-endothelial cell interactions are lacking." (PMID 28800782, 2017). "BDNF and VEGF-C expression levels were higher in tumor specimens than in normal tissue." (PMID 28771226, 2017). "Meanwhile, the level of BDNF mRNA and miR‐101 in the tumor samples from 36 patients with OA underwent correlation analysis, and a significant negative correlation was found between miR‐101 and the BDNF RNA level." (PMID 28904856, 2017). "On the mechanism, we believe that BDNF itself does not affect tumor growth, but can reduce hypoxia of tumor, thereby reducing the ABCG2 expression." (PMID 27852063, 2016). "Given that BDNF is induced by forced SFRP1 re-expression in both luminal-like SKBR3 and basal-like BT20 tumor cells, we hypothesized a putative tumor suppressive role of BDNF." (PMID 25036590, 2014). "BDNF increased the proportion of viable tumor cells (lower left quadrant), as compared with non-treated controls (DLD1; 64.1%→65.4%, SW480; 58.7%→67.1%, LoVo; 42.2%→55.8%)." (PMID 24801982, 2014).